SOWAHD (sosondowah ankyrin repeat domain family member D)
Synonyms: ANKRD58
Tractability: PROTAC: its protein half-life has been measured.
Gene: Protein-coding gene on chromosome X (119,758,588 to 119,760,202, forward strand). Ensembl gene ENSG00000187808.
Homologues: Orthologues: chimpanzee SOWAHD (99% identical), macaque SOWAHD (97% identical), pig SOWAHD (77% identical), dog SOWAHD (72% identical), rabbit SOWAHD (70% identical), mouse Sowahd (62% identical), rat Sowahd (62% identical), tropical clawed frog sowahd (32% identical), zebrafish sowahd (27% identical). Paralogues in human: SOWAHA (25% identical), SOWAHC (25% identical), SOWAHB (25% identical).
Diseases named in the same sentence as SOWAHD in open-access papers:
SOWAHD is named in the same sentence as 1 disease in open-access papers, as found by Europe PMC text mining. Sharing a sentence is not in itself a finding about the gene and the disease. The quoted sentences say what the papers report.
Allergy (1 paper, 2024). An allergy is an immune response or reaction to substances that are usually not harmful. "The specific SNPs of allergy and non-allergic groups were mainly in trafficking protein particle complex subunit 2 (TRAPPC2), Pirin (PIR), complement factor properdin (CFP), and sosondowah ankyrin repeat domain family member D (SOWAHD), however only TRAPPC2 and PIR were non-synonymous mutations." (PMID 39881721, 2024).